CXCL12 (C-X-C motif chemokine ligand 12)
Diseases named in the same sentence as CXCL12 in open-access papers (continued):
Sharing a sentence is not in itself a finding about the gene and the disease.
WHIM syndrome (23 papers, 2009 to 2026). "Collectively, these data suggest that WHIM syndrome is molecularly more complex than originally thought, as different mutations on receptors and different effects on CXCL12-mediated functions can lead to similar cellular phenotypes." (PMID 39035006, 2024). "The majority of the newly identified CXCR4 variants showed defects in CXCL12-induced internalization comparable to R334*, the most frequent and most studied WHIM syndrome variant." (PMID 35947323, 2022). "This process, together with the impaired desensitization of CXCR4, causes the gain of CXCL12/CXCR4 function that characterizes WHIM syndrome." (PMID 33466410, 2021). "The wart, hypogammaglobulinemia, infection, and myelokathexis (WHIM) syndrome is associated with inherited gain-of-function mutations in the CXCR4 gene that encodes a receptor for the CXCL12 chemokine." (PMID 27918748, 2016). "CXCR4-R334*, the most frequent WHIM syndrome variant, displayed a significant internalization defect at all CXCL12 concentrations used, while E343K, a missense variant found in WHIM syndrome patients, altered the internalization response only at lower ligand concentrations." (PMID 35947323, 2022). "Here, we thought to investigate this issue by providing mechanistic insights into the selective susceptibility to HPV pathogenesis displayed by patients who are immunosuppressed as a consequence of mutations in the CXCR4 gene encoding for the receptor of the CXCL12 chemokine (WHIM syndrome)." (PMID 27918748, 2016). "Recently, it was shown that defects in cell migration in WHIM syndrome patients may be caused by defects in the nanoclustering of the CXCR4 receptor at the cell membrane after CXCL12 activation, which is dependent on adequate β-arrestin 1 activation to induce remodeling of the actin cytoskeleton." (PMID 36725964, 2023). "Blocking of the CXCL12/CXCR4 signaling axis leads to the proliferation of primitive hematopoietic stem cells while excessive signaling by CXCR4 accounts for the molecular pathoetiology of the WHIM syndrome and is associated with tumor growth and metastasis formation." (PMID 20161793, 2010). "Burixaofr is also known to block CXCR4 and lower CXCL12 driven trafficking, with clinical trials underway for modulating inflammation in WHIM syndrome." (PMID 41256885, 2025). "A defect in CXCL12-mediated receptor internalization is one of the primary hallmarks of WHIM syndrome." (PMID 39575248, 2024). "In cases of WHIM syndrome with CXCR4 gain-of-function (GOF) variants, CXCR4 internalization is decreased, thus prolonging the interaction of CXCR4 and its ligand CXCL12, leading to hyperactive signaling." (PMID 35947323, 2022). "Along with this phosphorylation pattern, investigations of the pathogenesis of WHIM syndrome permitted us to assign a major role to GRK3 in regulating CXCL12-induced desensitization of CXCR4." (PMID 33466410, 2021). "Disruption of the CXCR4/CXCL12 balance such as that found in WHIM syndrome (Warts, Hypogammaglobulinemia, Immunodeficiency, and Myelokathexis syndrome) leads to deregulated neutrophil release into the circulation." (PMID 30356867, 2018). "From previous analyses of neutrophils derived from patients suffering from the WHIM syndrome it is anticipated that Cxcr4+/1013neutrophils would be also prone to an enhanced Cxcl12-dependent chemotaxis." (PMID 27111140, 2016). "Nef also profoundly downregulated the naturally truncated CXCR4 associated with WHIM syndrome and engineered variants of CXCR4 that resist CXCL12 induced internalization via an ubiquitinylation independent mechanism." (PMID 24489825, 2014). "A particular feature of the WHIM syndrome CXCR4 mutant receptors is a delay in the receptor sequestration that follows CXCL12 exposure, and substantial evidence has been presented that WHIM receptors are gain-of-function mutants causing prolonged signaling." (PMID 23734232, 2013).
WHIM syndrome (continued). "In Grk6-deficient mice, the neutrophils display enhanced SDF-1/CXCL12-induced chemotaxis in vitro, and thus display some of the hematological abnormalities of patients with WHIM syndrome." (PMID 19956569, 2009). "Based on these data, we propose that CXCL12-induced CXCR4 internalization can be used as a key parameter for the assessment of CXCR4 variant pathogenicity in vitro and as a potential disease biomarker for WHIM syndrome diagnosis." (PMID 36089616, 2022). "Disruption of the CXCR4/CXCL12 balance by inflammatory stimuli can increase neutrophil release into peripheral blood or can lead to leukostasis in the bone marrow such as found in WHIM syndrome." (PMID 30356867, 2018). "Similarly, NK cells from mice displaying the most common mutation of the CXCR4 gene associated with WHIM syndrome show enhanced migration to CXCL12 that is linked to impaired CXCR4 desensitization and internalization after CXCL12 stimulation." (PMID 27766097, 2016). "When deregulated, as in the WHIM syndrome, the CXCL12/CXCR4 pathway can trigger HPV-induced transformation as a result of elevated levels of oncoprotein-induced signaling and down-regulation of DNA damage response pathways associated with cell hyperproliferation." (PMID 27918748, 2016). "Given that GRK3 contributes to the CXCL12-promoted phosphorylation at S346/347 and that GRK3 prefers acidic residues N-terminal to the phospho-site, we also generated a HA-tagged E343K mutant (HA-CXCR4-E343K), which corresponds to a recently discovered WHIM syndrome-associated mutation." (PMID 23734232, 2013). "The cytoplasmic tail of CXCR4 is truncated in WHIM syndrome, resulting in reduced internalization,higher number of CXCR4 surface receptors, and enhanced chemotaxis of leukocytes in response to CXCL12." (PMID 25909600, 2015). "Leukocytes from patients with WHIM syndrome display impaired CXCR4 internalization and enhanced chemotaxis in response to its unique ligand SDF-1/CXCL12, which likely contribute to the clinical manifestations." (PMID 19956569, 2009). "Early studies that have identified the role of CXCL12/CXCR4 in human immunodeficiency virus (HIV) pathogenesis, later in cancer progression and metastasis and more recently in the pathogenesis of WHIM syndrome have facilitated research devoted to the regulation of this signalling axis." (PMID 33466410, 2021).
prostate tumor (22 papers, 2011 to 2024). "As shown by microarray analysis and immunohistochemistry, murine epithelial cells from these PTEN-deficient prostate tumors display increased expression of CXCL12 and CXCR4 as compared to the normal prostate glands of PTEN+/+ and PTEN+/− mice." (PMID 23902739, 2013). "Conversely, paracrine signalling by TGFβ and CXCL12/SDF-1 have also been implicated in prostate tumour progression." (PMID 21533155, 2011). "Our studies provide new insights into the role of HIC1 in normal prostatic epithelial-stromal interactions through direct repression of CXCL12 and new mechanistic clues on how its loss of function through promoter hypermethylation during aging could contribute to prostatic tumors." (PMID 33227080, 2020). "Stimulation by CXCL12 was found to promote prostate tumor migration across monolayers of bone marrow endothelial cells, increase invasion through basement membranes, as well as adhesiveness towards osteosarcomas." (PMID 32585812, 2020). "In this study we detail how the synthetic androgen R1881 regulates the CXCR4/CXCR7 axis to control CXCL12-mediated motility of LNCaP prostate tumor cells." (PMID 25884570, 2015). "Recently, it was discovered that fibroblasts derived from mouse prostate tumors stimulated by BMPs can increase angiogenesis via the upregulation of the chemokine SDF1α/CXCL12." (PMID 23840733, 2013). "Taken together, these studies emphasize the clinical significance of CXCL12/CXCR4 expression in prostate tumor progression." (PMID 23902739, 2013). "Indeed, CXCL12 plays important roles in prostate tumor cell homing, re-establishment, and proliferation in metastatic sites through their modulatory effects on tumor adhesiveness and migration." (PMID 32585812, 2020). "In summary, our findings in androgen-sensitive prostate tumor cells reveal that androgens modulate cell motility in a dose-dependent manner in response to chemokine CXCL12, and that they do so by regulating the expression of chemokine receptors CXCR4 and CXCR7." (PMID 25884570, 2015). "Notably, while recruitment of macrophages into tumors by CAFs is operative in various cancer types, the molecular pathways are distinct: In primary in vitro cultures, CAFs isolated from human prostate tumors were found to recruit monocytes by secreting stromal cell-derived factor 1 (SDF1)/CXCL12." (PMID 31428105, 2019). "We recently reported that a chemokine CXCL12, also known as stromal-cell derived factor 1 (SDF-1), signaling via receptors CXCR4 and CXCR7 and activating tumor cell growth and invasion pathways, is responsible for accelerated prostate tumor growth in obesity." (PMID 33753872, 2021). "Apart from these, the enhanced activation of the CXCL12/CXCR4 axis in metastatic sites instituted an angiogenic switch and promoted prostate tumor metastasis that is mediated by a decreased expression of the glycolytic phosphoglycerate kinase 1 (PGK1) enzyme." (PMID 32585812, 2020). "Further, in an ex vivo prostate tumor model, celecoxib suppressed intra-tumoral production of the Treg/MDSC-attractant CXCL12 and Treg-attractant CCL22, while increasing the production of the cytotoxic T lymphocyte (CTL) attractant CXCL10." (PMID 32824865, 2020). "In our dataset, we observed high expression of CXCL12 in fibroblasts, CCL2 in pericytes, and CCL3,4, and 5 in epithelial and tumor cells, suggesting a potential role of fibroblasts and pericytes in recruiting monocytes to the prostate tumor." (PMID 36750562, 2023). "In the prostate tumor microenvironment, PGE2 induces CXCL12 expression in prostate stromal cells." (PMID 32824865, 2020). "Human and murine prostate tumors have been previously reported to express CCL2, CCL5 and CXCL12." (PMID 27177227, 2016).
psoriasis (22 papers, 2014 to 2026). An autoimmune condition characterized by red, well-delineated plaques with silvery scales that are usually on the extensor surfaces and scalp. "In contrast to the inflammatory pattern observed in psoriasis, inflammatory changes are most pronounced in fibroblasts, pericytes, and keratinocytes in AD, and fibroblasts interact with Th2/Th22 cells via CXCL12." (PMID 39420283, 2024). "For example, CXCL12 plays pivotal roles in immune regulation and is involved in autoimmune diseases such as psoriasis and lupus." (PMID 38338982, 2024). "We further observed the elevation of serum CXCL12 in psoriasis patients compared to healthy controls." (PMID 37736772, 2023). "In previous studies, the C-X-C motif receptor (CXCR4)/C-X-C motif ligand 12 (CXCL12) axis was reported to participate in psoriasis-like inflammation both by promoting keratinocyte proliferation and recruiting T cells." (PMID 37809065, 2023). "Accordingly, CXCL12 may be involved in the progression from PsO vulgaris to PsA, with MTX therapy reducing CXCL12 expression and disease severity, suggesting CXCL12 as a potential biomarker for psoriasis severity." (PMID 39070795, 2024). "This aligns with the normalization of CXCL12 serum level after therapeutic targeting of IL-17A and may provide an explanation for the decreased level of CXCR4hi neutrophils following effective psoriasis treatment." (PMID 37736772, 2023). "Fibroblasts produced a number of chemokines (CCL13, CCL19, CCL2, CCL8, CXCL1, CXCL12, CXCL2, CXCL3) that linked to receptors expressed by myeloid cells and T cells, suggesting an important role for fibroblasts in recruiting immune cells in psoriasis." (PMID 37308489, 2023). "Other reports have shown a beneficial role of the CXCL12/CXCR4 axis in psoriasis." (PMID 31507535, 2019). "Furthermore, CXCL12 is induced in ECs in response to psoriasis-related stimuli including IL-17A." (PMID 37736772, 2023). "Finally, the CXCR4/CXCL12 signaling axis plays a pivotal role in numerous biological processes and an overexpression of CXCR4 has been associated with several diseases including skin inflammatory diseases such as psoriasis and AD." (PMID 34912758, 2021). "Although several chemokines, such as CCL13, CXCL12, CXCL10, CCL27, and CCR6, have been identified in the context of psoriasis, CXCL10, in particular, has been suggested as a biomarker for psoriasis progression." (PMID 38829444, 2024). "Both CXCL12 inhibition and CXCR4 antagonism ameliorated psoriasis-like lesions in IMQ-treated mice, including epidermal thickness, and proportion of infiltrating Ly6G+CXCR4hi neutrophils." (PMID 37736772, 2023). "We found one crossover locus of IL13 for psoriasis, two crossover loci BLK and ITGAM/ITGAX genes for SLE and four crossover loci near TFPI, CYP2A1, PECAM1, and CXCL12 for CAD data set." (PMID 32779262, 2020). "The appearance of CXCL12, CCL19, and ANGPTL4 in both directions indicates the positive feedback signaling between keratinocytes and myeloid cells, which likely amplifies the pathogenesis of the psoriasis." (PMID 39999288, 2025). "The CXCL12/CXCR4 pathway is known to be involved in chronic skin inflammatory diseases such as psoriasis; however, its effects on hair inflammation have not been studied." (PMID 38338982, 2024). "Furthermore, the inflammatory indicators found to be upregulated in psoriasis MCs, such as ATF4, CXCL12, LTA, TACR1, TLR4, and CTSB, interestingly share IL-1β as a common modulator." (PMID 37681909, 2023). "We further showed induction of CXCL12 in HMEC-1 cells by either mixture of pro-inflammatory cytokines (IL-17A, IL-22, TNF, IL-1α, and oncostatin M), or serum from active psoriasis patients." (PMID 37736772, 2023).
psoriasis (continued). "Through single-cell transcriptomic and spatial transcriptomic techniques, Ma further revealed that in psoriasis, SFRP2+ fibroblasts transition from a fibrotic state to an inflammatory state by producing C-C motif chemokine ligand (CCL) 13, CCL19, C-X-C motif chemokine ligand (CXCL) 1, and CXCL12." (PMID 39420283, 2024).
Cerebral ischemia (21 papers, 2014 to 2025). Restriction of arterial blood supply to the brain associated with insufficient oxygenation to support the metabolic requirements of the tissue. "CXCR4 encodes a well-known receptor for chemokine CXCL12, which is mainly produced by damaged neurons after cerebral ischemia." (PMID 34154653, 2021). "CXCL12 has been proven to be broadly neuroprotective, with roles in modulating inflammatory responses and promoting neuronal regeneration after cerebral ischemia." (PMID 41091415, 2025). "CXCL12/SDF-1, which is highly expressed at the site of cerebral ischemia, can promote neural repair and regeneration by recruiting neural progenitor cells." (PMID 39206161, 2024). "CXCL12 expression increased in the acute phase of cerebral ischemia and decreased after 7 days in MCAO mice." (PMID 34881088, 2021). "The expression of CXCL12 was significantly upregulated after cerebral ischemia, leading to chemotaxis of endothelial progenitor cells expressing CXCR4." (PMID 33381162, 2020). "Previous studies have shown that expression of CXCL12 in astrocytes is upregulated within 7 days after cerebral ischemia in newborn mice." (PMID 33381162, 2020). "Regarding pathological conditions, CXCL12 is up-regulated in neurons and endothelia in the area of penumbra following brain ischemia, thus facilitating angiogenesis, neurogenesis, and synaptic transmission." (PMID 33213069, 2020). "CXCL12 and CXCL13 have been associated with a deleterious role during cerebral ischemia attracting lymphocytes." (PMID 30258527, 2018). "Therefore, OPCs transplantation provided an approach to maintain CXCL12 after the post-acute phase of cerebral ischemia." (PMID 34881088, 2021). "Also, it is observed in cerebral ischemia that CXCL12 is upregulated under ischemic conditions, thereby inducing monocytes to gather in the ischemic penumbra and a subsequent inflammatory response." (PMID 24676944, 2014). "By monitoring the site of high CXCL12/SDF-1 expression after VaD, the site of cerebral ischemia can be localized in real time." (PMID 39206161, 2024). "One of the chemokines, which is present after cerebral ischemia, is the chemokine group CXC ligand 12 (CXCL12), also called stromal cell-derived factor (SDF-1), which is mainly produced by damaged neurons." (PMID 31514749, 2019). "CXCL12-EPC treatment significantly reduced brain atrophy and improved neurobehavioral function at 5 weeks after brain ischemia." (PMID 29751775, 2018).
non-small cell lung carcinoma (21 papers, 2006 to 2025). A group of at least three distinct histological types of lung cancer, including non-small cell squamous cell carcinoma, adenocarcinoma, and large cell carcinoma. "Patients with high CXCL12 (C-X3-C Motif Chemokine Ligand 12) expression in their primary non-small cell lung cancer (NSCLC) also have a higher risk of developing brain metastases." (PMID 36527157, 2022). "A more direct evaluation of the role that the CXCL12 axis plays in chemoresistance indicates that the upregulation of CXCR4 in non-small cell lung carcinoma (NSCLC) mediates Gefitinib-resistance associated with EMT." (PMID 33363463, 2020). "CXCL12, derived from CD248-expressing cancer-associated fibroblasts, mediated M2-polarized macrophages to promote non-small cell lung cancer progression." (PMID 38232115, 2024). "This study investigated the value of tumor CXCL12 expression to predict prognosis and indicate adjuvant chemotherapy in non-small cell lung cancer patients." (PMID 37227446, 2023). "In line with this, non-small cell lung cancer (NSCLC) express high CXCL12 levels and especially recruits CD4+CD69+CXCR4+ T cells with an increased ratio of regulatory T cells." (PMID 30319622, 2018). "Hypermethylation of CXCL12 in non-small cell lung cancer has also been reported to be a poor prognostic marker." (PMID 27899617, 2017). "Investigations have revealed that the presence of CXCL12 and its receptor CXCR4 in non-small cell lung cancer correlates with tumor development, infiltration, and metastasis." (PMID 40243586, 2025). "In another study, CXCL12, the CXCR4 ligand, was expressed in most non-small cell lung cancer tissue sections obtained from stage IA to IIB non-small cell lung cancer patients undergoing operation." (PMID 35740564, 2022). "Additionally, non-small cell lung cancer NCI-H358 cells, which overexpress EGFR, undergo significantly greater apoptosis when treated with the CXCL12–Ctx KineTAC than when treated with Ctz IgG." (PMID 36138170, 2023). "Signaling between the chemokine receptor CXCR4 and its ligand SDF-1, otherwise known as chemokine ligand (CXCL)-12, contributes to tumor growth, angiogenesis, invasion and metastases in several solid tumors, including non-small cell lung cancer." (PMID 25775124, 2015).